ANXA1 (annexin A1)
Diseases named in the same sentence as ANXA1 in open-access papers (continued):
Sharing a sentence is not in itself a finding about the gene and the disease.
osteosarcoma (4 papers, 2007 to 2021). A usually aggressive malignant bone-forming mesenchymal neoplasm, predominantly affecting adolescents and young adults. "Down regulation of HSPA5 can promote ANXA1 and repress PSAT1 expression, which inhibiting the osteosarcoma cell proliferation and inducing cell apoptosis." (PMID 34412642, 2021). "Two candidate biomarkers, ANXA1 and PSAT1, for the prognosis of osteosarcoma were detected separately on the basis of WGCNA and LASSO model." (PMID 33291071, 2020). "Suppression of HSPA5 effectively upregulated ANXA1 and inhibited PSAT1, resulting in osteosarcoma cell proliferation arrest and apoptosis." (PMID 33291071, 2020).
pancreatic ductal adenocarcinoma (4 papers, 2014 to 2021). An infiltrating adenocarcinoma that arises from the epithelial cells of the pancreas. "Our results confirmed overexpression of ANXA1 mRNA and protein in pancreatic ductal adenocarcinoma, suggesting ANXA1 up-regulation involved in pancreatic tumorigenesis." (PMID 25038797, 2014).
pneumonia (4 papers, 2020 to 2024). An acute, acute and chronic, or chronic inflammation focally or diffusely affecting the lung parenchyma, caused by an infection in one or both of the lungs (by bacteria, viruses, fungi, or mycoplasma.). "In fact, the benefits of AnxA1, another proresolving GC-induced protein, in pneumonia were recently described and support this concept." (PMID 35159341, 2022). "AnxA1 level at admission was significantly higher in SCAP patients than in non-SCAP patients (p < 0.001) irrespective of CAP etiology and was positively correlated with Pneumonia Severity Index and Confusion, Uremia, Respiratory Rate, Blood Pressure, and Age ≥ 65 Years score." (PMID 36766501, 2023). "However, it is unclear whether AnxA1 expression has predictive value for nonviral pneumonia." (PMID 36766501, 2023).
sickle cell disease (4 papers, 2016 to 2025). Sickle cell anemias are chronic hemolytic diseases that may induce three types of acute accidents: severe anemia, severe bacterial infections, and ischemic vasoocclusive accidents (VOA) caused by sickle-shaped red blood cells obstructing small blood vessels and capillaries. "Interestingly, Ansari's research on sickle cell disease revealed that ANXA1‐induced activation of macrophage FPR2/ALX axis, leading to differentiation of M2 polarisation and conferring a protective effect." (PMID 39993960, 2025).
adenoma (3 papers, 2008 to 2024). A neoplasm arising from the epithelium. "In the LNM-positive group compared to the control adenoma, there were significant increases in gene expression for CCL15, SSX1, and KRT5 genes, alongside significant decreases in HLA-E, ITPK1, ANXA1, and TXNIP genes across the head, proximal stalk, and distal stalk regions." (PMID 38256174, 2024). "Tyrosine phosphorylation of annexin A1 has been observed in pituitary carcinomas but not adenomas." (PMID 18637184, 2008).
airway hyperresponsiveness (3 papers, 2018 to 2023). "AnxA1 deficient mice exhibit spontaneous airway hyperresponsiveness and exacerbated allergen responses and AnxA1 mimetics inhibit eosinophil recruitment." (PMID 31396220, 2019).
atopic dermatitis (3 papers, 2019 to 2025). "However, acknowledging the ongoing importance of LC in atopic dermatitis, additional research is needed to elucidate how significant genetic factors (Trp73, Orm-1, Chi3l3, Ccl20, AnXa1, Alox5, Ccr1, and Fcεr1a, etc.)identified in our study may interact with LC function and the disease process." (PMID 38834629, 2024). "Given the anti-inflammatory properties of AnxA1, we evaluated the effect of a lack of endogenous AnxA1 in a model of atopic dermatitis induced by ovalbumin." (PMID 30650525, 2019). "This work evaluated the lack of endogenous AnxA1 in the progression of ovalbumin (OVA)-induced atopic dermatitis (AD)-like skin lesions." (PMID 30650525, 2019).
cholangiocarcinoma (3 papers, 2014 to 2025). A carcinoma that arises from the intrahepatic biliary tree (intrahepatic cholangiocarcinoma) or from the junction, or adjacent to the junction, of the right and left hepatic ducts (hilar cholangiocarcinoma). "To explore this, we measured aspartate and glutamate production in cell lysates from ANXA1-knockdown cholangiocarcinoma cells, as well as tissue lysates from subcutaneous xenograft tumors in mice." (PMID 40390008, 2025). "ANXA1 was recently reported to be a marker for cholangiocarcinoma." (PMID 37735492, 2023). "Although these findings were consistent with results showing that PSC may progress to cholangiocarcinoma, the role of ANXA1 in cholangiocarcinoma remains to be determined." (PMID 37735492, 2023).
colon adenocarcinoma (3 papers, 2011 to 2013). "In line with this view, an increase of AnxA1 expression has been associated with the development of tumor metastasis and colonic adenocarcinoma." (PMID 22723974, 2012). "An important recent advance has been that sodium butyrate has been found to up-regulate the expression of annexin A1 (ANXA1) in human colon adenocarcinoma cells." (PMID 24086397, 2013). "Lecona and colleagues suggested that butyrate can up-regulate the expression of annexin A1 in human colon adenocarcinoma cells." (PMID 24086397, 2013). "Lecona and colleagues demonstrated that butyrate could up-regulate the expression of ANXA1 in human colon adenocarcinoma cells." (PMID 24086397, 2013).
depression (3 papers, 2021 to 2024). "The present study showed that multiple pontine genes, including Anxa1, Serpinf1, Arrb1, Cplx2, Nrg1, and Psen1 were altered in a model of depression." (PMID 39135796, 2024). "This highlights ANXA1’s intricate involvement in the neuroendocrine regulation of stress responses and its potential as a target for understanding and treating depressive disorders." (PMID 38639785, 2024). "Anxa1 plays a crucial role in chronic corticosterone-induced depression-like behaviors and impairment in hippocampal-dependent memory." (PMID 33628784, 2021). "However, upregulated Anxa1 expression has been reported in the hippocampal region when depression occurs, and the hippocampus belongs to the limbic system." (PMID 39135796, 2024). "ANXA1 also has neuroendocrine functions within the context of depression." (PMID 38639785, 2024). "Therefore, we speculate that there is a possibility that the expression of Anxa1 in the pons and hippocampus is inconsistent when depression occurs." (PMID 39135796, 2024). "To date, there have been no studies on the expression of the Anxa1 gene in the pons of a depression model." (PMID 39135796, 2024). "Notably, the absence of ANXA1 led to improvements in anxiety and depression-like behaviors, maintenance of hippocampal homeostasis, and prevention of neuronal damage associated with depression." (PMID 38639785, 2024).
dermatitis (3 papers, 2019 to 2024). An inflammatory process affecting the skin. "This present research is the first to find out that spinal upregulations of TfR1 expression and iron content after dermatitis and cholestasis are reversed by ANXA1, IL-17 neutralization and IL-17R antagonism, respectively." (PMID 38790419, 2024). "Herein, we report that spinal expression of ANXA1 is down-regulated in mice with dermatitis-induced itch and cholestatic itch." (PMID 38790419, 2024). "Repetitive injections of ANXA1-derived peptide Ac2-26 (intrathecal, 10 μg) reduce itch-like scratching behaviors following dermatitis and cholestasis." (PMID 38790419, 2024). "Additionally, Anxa1 regulates T cell activity in skin inflammation, and Ccl20 and Trp73 are involved in inflammatory responses." (PMID 38834629, 2024). "Additionally, ANXA1 suppressed IL-17 production, IL-17R expression and astrocyte activation in the spinal dorsal horns of mice with dermatitis and cholestasis." (PMID 38790419, 2024). "Taken together, this current research indicates that ANXA1 protects against the beginning and maintenance of long-term dermatitis-induced itch and cholestatic itch, which may occur via the spinal suppression of IL-17-mediated neuroinflammation, astrocyte activation and iron overload." (PMID 38790419, 2024). "Overall, these behavioral and biochemical data emphasize that ANXA1 restricts the initiation and maintenance of long-term pruritus via blocking spinal IL-17-mediated astrocyte activation and subsequently resolving neuroinflammation in both dermatitis and cholestasis." (PMID 38790419, 2024). "Interestingly, the known mechanism for MP-associated skin disorder, Stevens-Johnson syndrome, is attributed to cytotoxic T-cell-mediated immune response, cell death mediators, such as FasL and annexin A1 from the apoptotic keratinocytes in skin tissue, not by invading foreign Mycoplasma." (PMID 31860676, 2019).
endothelial dysfunction (3 papers, 2014 to 2025). In vascular diseases, endothelial dysfunction is a systemic pathological state of the endothelium (the inner lining of blood vessels) and can be broadly defined as an imbalance between vasodilating and vasoconstricting substances produced by (or acting on) the endothelium. "Inflammatory mediators like Annexin A1 (ANXA1) were suggestive of endothelial dysfunction and liver transplant-associated injury." (PMID 40867840, 2025). "This dysfunction was significantly exacerbated by silencing ANXA1, suggesting that the loss of ANXA1 might contribute to the endothelial dysfunction during SAE." (PMID 39727329, 2024).
epilepsy (3 papers, 2019 to 2024). A brain disorder characterized by episodes of abnormally increased neuronal discharge resulting in transient episodes of sensory or motor neurological dysfunction, or psychic dysfunction. "In particular, genes such as ANXA1, CNTN6, HLA-B, PCDH19, and PCDH10, have been linked to ASD, epilepsy, ID, and other neuropsychiatric disorders, were significantly upregulated or downregulated and warrant further investigation." (PMID 31921404, 2020). "Besides, another study also revealed a beneficial role of ANXA1 in epilepsy." (PMID 38585359, 2024). "Furthermore, systemic pilocarpine-induced SE in rats increased ANXA1 levels in the brain in the acute phase (24 h), gradually decreasing in the latency period (72 h to 2 weeks) and then increasing in the chronic phase (30 days), suggesting a regulatory role of ANXA1 in epilepsy." (PMID 30755225, 2019).
experimental autoimmune encephalomyelitis (3 papers, 2009 to 2025). An autoimmune demyelinating disease of the central nervous system that is produced experimentally in animals by the injection of homogenized brain or spinal cord in Freund's adjuvant. "In contrast, in mouse models of allergic airway inflammation and experimental autoimmune encephalomyelitis AnxA1-deficient mice showed decreased Th1/Th17 polarization of T cells and reduced disease activity, suggesting proinflammatory effects of AnxA1." (PMID 36311242, 2022).
fibrosis (3 papers, 2011 to 2017). the formation of excess fibrous connective tissue in an organ or tissue in a reparative or reactive process. "In particular, AnxA1 mRNA was significantly lower in subjects with bridging fibrosis, as compared to those with mild/moderate pericentral or -portal fibrosis or without fibrosis." (PMID 24668763, 2014).
glomerulosclerosis (3 papers, 2014 to 2022). A hardening of the kidney glomerulus caused by scarring of the blood vessels. "The final fundamental result of our study is the accelerated development of glomerulosclerosis and tubulointerstitial fibrosis in the nephritic AnxA1-deficient mice." (PMID 36311242, 2022). "We also demonstrated that ANXA1 positively correlated with the degree of glomerular sclerosis in all patients with various types of glomerular disorders and crescentic formation in patients with primary GN: proliferative GN and secondary GN." (PMID 24591769, 2014). "In addition, the levels of urinary ANXA1 also correlated well with glomerular sclerosis in group 1 (r = 0.43, P < 0.01) and group 3 (r = 0.58, P < 0.05)." (PMID 24591769, 2014). "Combined all patients with various glomerular disorders, urinary ANXA1 protein levels positively correlated with the score of glomerular proliferation (r = 0.67, P < 0.001), interstitial inflammation (r = 0.54, P < 0.005), and glomerular sclerosis (r = 0.44, P < 0.001)." (PMID 24591769, 2014).
Glucose intolerance (3 papers, 2013 to 2024). Glucose intolerance (GI) can be defined as dysglycemia that comprises both prediabetes and diabetes. "ANXA1 knockout (ANXA1−/−) mice fed a high sugar, high fat diet had greater glucose intolerance compared to wild-type mice fed the same high sugar, high fat diet." (PMID 39432712, 2024).
Hyperglycemia (3 papers, 2012 to 2023). An increased concentration of glucose in the blood. "Analysis of placentas exposed to an adverse environment, such as hyperglycemia, showed similar outcomes associated with ANXA1 deficiency in the nucleus and cytoplasm of GDM samples." (PMID 37373303, 2023). "To determine the effects of hyperglycemia on skin fibroblasts we examined the expression and localization of ANXA1 by Western blot analysis and immunofluorescence microscopy." (PMID 23029153, 2012). "As these effects were detected in the placenta samples from AnxA1−/− mice, our data strongly suggest a protective role for ANXA1 in placental physiology, which can be mitigated in certain adverse conditions, such as hyperglycemia." (PMID 37373303, 2023). "Interestingly the N-terminal peptide of ANXA1, Ac2-26 was able to stimulate direct migration of WS1 cells in high glucose treatment possibly due to the increased receptor expression observed in hyperglycemia conditions." (PMID 23029153, 2012). "However, because expression of gluconeogenic enzymes was not significantly altered in HFD ANXA1 KO mice compared to diet-matched WT mice, data suggest that the hyperglycemia of ANXA1 KO mice on HFD is unlikely to be the result of increased gluconeogenesis." (PMID 24312665, 2013).
laryngeal carcinoma (3 papers, 2014 to 2025). Carcinoma that arises from the laryngeal epithelium. "Our results established, for the first time, the role of FPR2/ALX in laryngeal carcinoma cells as demonstrated by ultrastructural analyses showing the co-localization of ANXA1/FPR2." (PMID 25490767, 2014). "Overall, this study identified potential roles for the molecular mechanism of the ANXA1/FPR2 interaction in laryngeal cancer, including its relationship with the prostaglandin pathway, providing promising starting points for future research." (PMID 25490767, 2014). "In this report, we showed that ANXA1 protein is down-regulated in human laryngeal carcinoma and can regulate tumor growth in a paracrine manner that is mediated by the receptor FPR2/ALX." (PMID 25490767, 2014). "In the inflammatory cells of human laryngeal carcinoma tissue samples, ANXA1/FPR2 expression was markedly exacerbated; however, in laryngeal carcinoma cells, this expression was down-regulated." (PMID 25490767, 2014). "A detailed understanding of the function and importance of IGFBP7 and ANXA1 may help to further elucidate the biological mechanisms of laryngeal carcinoma and support the development of early diagnosis and preventive treatment." (PMID 38893148, 2024). "Loss of ANXA1 and FPR2/ALX expression was detected in laryngeal carcinoma cells." (PMID 25490767, 2014). "In these inflammatory cells of peritumoral and tumor samples, ANXA1/FPR2 expression was markedly exacerbated, however, in laryngeal carcinoma cells, this expression was down-regulated." (PMID 25490767, 2014). "The tumor-activated inflammatory cells appear to increase the synthesis of ANXA1/FPR2 proteins as an anti-inflammatory response mechanism to resolve the inflammation and proliferation in laryngeal cancer." (PMID 25490767, 2014). "Overall, our in vivo data indicated that mast cells and neutrophils, under activation by the tumor microenvironment, demonstrate up-regulation of ANXA1/FPR2 as an anti-inflammatory response mechanism to resolve inflammation and proliferation in laryngeal cancer." (PMID 25490767, 2014).
leishmaniasis (3 papers, 2020 to 2024). Infectious disease that is transmitted through the bite of hematophagous female phlebotomine sand flies. "In a model of experimental leishmaniasis, footpad infections of wildtype and ANXA1-/- mice were performed using L. major either alone or in combination with LeishEXO." (PMID 39076982, 2024). "To further decipher ANXA1’s role in the immune response to leishmaniasis, we aimed to characterize its involvement in early inflammatory events following Leishmania infection." (PMID 39076982, 2024). "Our data demonstrate the relevance of annexin-A1 in the regulation of apoptosis and phagocytosis in leishmaniasis." (PMID 34431955, 2021). "This study aimed to determine the number of macrophages and apoptotic cells and perform annexin-A1 detection in patients with leishmaniasis." (PMID 34431955, 2021). "The present study aimed to determine the number of macrophages and apoptotic cells in the skin lesions of patients with leishmaniasis and analyze ANXA1 detection in these cells." (PMID 34431955, 2021). "Given the primary constituents of exosomes are lipids and phospholipids, which directly interact with negative-charged phospholipid-sensing annexin receptors, we hypothesized that ANXA1 was involved in the exacerbation of leishmaniasis by leishmanial exosomes (LeishEXO)." (PMID 39076982, 2024). "This research describes LeishEXO’s utilization of the ANXA1/FPR axis to facilitate parasitic internalization and pathogenesis, which may be leveraged in the development of therapeutics for leishmaniasis." (PMID 39076982, 2024).
lymphoma (3 papers, 2006 to 2022). A malignant (clonal) proliferation of B- lymphocytes or T- lymphocytes which involves the lymph nodes, bone marrow and/or extranodal sites. "Moreover, it was demonstrated in L5178Y tk+/− mouse lymphoma cells treated with DNA-damaging agents that the quantity of nuclear ANXA1 increased while cytoplasmic ANXA1 levels decreased, suggesting that nuclear translocation of this protein occurs in response to the signaling of damaged DNA." (PMID 35805141, 2022).
meningioma (3 papers, 2021 to 2023). A generally slow growing tumor attached to the dura mater. "Using these diagnostic markers like MUC1, S100A11, and ANXA1, this approach could be tested out as an alternative to confirm the early prognosis of Meningioma." (PMID 37770851, 2023).
metastasis (3 papers, 2022 to 2023). The spread or migration of cancer cells from one part of the body (where they first appeared) to another. "High AnxA1 expression was shown to be associated with increased serosal invasion and peritoneal metastasis." (PMID 36766501, 2023). "The association between lymph node positive recurrence-free patient survival and distant metastasis-free patient survival and ANXA1 and FPR1 and FPR2 expression was examined using TCGA datasets." (PMID 35382852, 2022). "Indeed, Annexin-A1 down regulation in HNSCC was associated with poor histological differentiation, advanced T stages, hypopharyngeal localization and lymphoregional lymph node metastasis." (PMID 37954869, 2023).
multiple myeloma (3 papers, 2020 to 2026). "In some patients, BCMA-negative relapse has been associated with upregulation of annexin A1 (ANXA1), a molecule that promotes myeloma growth and disrupts CAR-T targeting; preclinical inhibition of ANXA1 restores CAR-T sensitivity." (PMID 41596492, 2026).
myocardial ischemia (3 papers, 2012 to 2026). A disorder of cardiac function caused by insufficient blood flow to the muscle tissue of the heart. "In models of myocardial ischemia/reperfusion and permanent coronary occlusion, AnxA1 limits injury, an effect in acute phases attributable to restrained leukocyte trafficking and activation." (PMID 41516407, 2026). "FPR2-selective peptidomimetics derived from Annexin A1—CR-AnxA12–50 and CR-AnxA12–48—have each conferred robust protection against acute myocardial ischemia–reperfusion (I/R) injury in murine models." (PMID 41516407, 2026).